BDNF (brain derived neurotrophic factor)
Diseases named in the same sentence as BDNF in open-access papers (continued):
Sharing a sentence is not in itself a finding about the gene and the disease.
breast cancer (continued). "Although BDNF has been postulated as a putative oncogene, the co-regulation with SFRP1 indicates a potential suppressive function in breast cancer." (PMID 25036590, 2014). "Similar expression patterns were demonstrated in choriocarcinoma cells, whereas both BDNF and NT4/5 contributed to cellular survival of breast cancer." (PMID 22911740, 2012). "Expression levels of BDNF and BDNF-correlated genes CCND2, DUSP6, EGR1, KLF10 and PTPRF are altered in breast cancer." (PMID 19737418, 2009). "In the present study all resulting mammary tumors expressed mRNA for the neurotrophins NGF and BDNF and neurotrophin receptors TrkA, TrkB and p75NTR." (PMID 19173004, 2009). "Further in vivo study revealed that combined therapy with CUR and CIS inhibited the mammary tumor growth accompanied by increased peroxisome proliferator-activated receptor gamma (PPAR-γ) expression and decreased brain-derived neurotrophic factor (BDNF) expression in mammary tumors." (PMID 35216255, 2022). "In our in vitro model, BDNF expression increased in breast cancer cells after exposure to 60% and 80% O2 but did not increase in 40% O2 group, probably related to lower ROS increment right after exposure." (PMID 32183322, 2020). "In addition, curcumin pre-treatment has been observed to inhibit the growth of breast cancer cells in rats via activation of PPAR-γ and decreasing the expression of brain-derived neurotrophic factor (BDNF)." (PMID 30347782, 2018). "Using an in vitro system, we found that MDA-MB-231, but not other breast cancer cell lines, secreted BDNF into the culture medium (supplementary reference 4)." (PMID 28604807, 2017). "Thus, in breast cancer cells, NTF3 is capable of activating TrkB to induce anoikis resistance to the same extent as BDNF, supporting our hypothesized role of NTF3 in TrkB-mediated anoikis resistance." (PMID 23185507, 2012). "To determine, whether BDNF, a potential novel target gene of the tumor suppressor SFRP1, may also mediate inhibiting effects on cell proliferation of breast cancer cells, we generated a stable BDNF over-expressing breast cancer in vitro model using BT20 breast cancer cells." (PMID 25036590, 2014). "Previously, we have measured the BDNF level in the cultured media of different breast cancer cell lines (MCF-7, SK-BR-3, MDA-MB-231, MDA-MB-468) and the results showed that only MDA-MB-231 cells, but not other cell types, secreted BDNF into the culture media in a time-dependent manner." (PMID 28604807, 2017). "Our previous study targeting the molecular mechanisms that occur in paired tumor specimens obtained from patients with and without recurrence, have suggested that the BDNF signaling pathway is involved in the up-regulation of genes that are present in stage II and stage IIIA recurrent breast cancer." (PMID 28800782, 2017). "Next, we wanted to decipher whether the positive correlation between SFRP1 and BDNF expression on the one hand and the negative correlation between SFRP1 and LY96 expression on the other hand is also detectable in human breast cancer." (PMID 25036590, 2014).
Hypertension (69 papers, 2010 to 2025). The presence of chronic increased pressure in the systemic arterial system. "The association betweenmiR-1-3p expression and BDNF levels has been investigated in patients withessential hypertension." (PMID 39077334, 2024). "BDNF activity, the amount of BDNF expressed by the regulating genes, was positively correlated with high blood pressure and negatively associated with smoking." (PMID 39081995, 2023). "The sBDNF tertile was significantly associated with BDNF Val66Met polymorphism, age, current unemployment, hypertension, current smoking, and LVEF." (PMID 35459929, 2022). "Exercise causes the release of adrenaline, glucocorticoid, and cortisol, which play neuroprotective roles by increasing the secretion of brain-derived neurotrophic factor, improving memory ability, and preventing neurologic dementia caused by hypertension." (PMID 34886423, 2021). "We postulated that hypertension is associated with decreased hippocampal BDNF, which can be restored by exercise‐mediated upregulation of fibronectin type‐II domain‐containing 5 (FNDC5)." (PMID 31883222, 2019). "Given that hypertension is associated with neurocognitive deficits, we examined the expression of BDNF, TrkB, FNDC5, AT1R, and MR in the CA1‐3 and DG regions of the hippocampus." (PMID 31883222, 2019). "It should be stressed that low levels of circulating BDNF were found in patients with cardiovascular disorders associated with hypertension." (PMID 31341469, 2019). "Logistic regression analysis was performed to test the associations of BDNF, musclin, leptin and irisin with hypertension." (PMID 31133682, 2019). "Recent studies including ours have demonstrated that BDNF is associated with autonomic function, nocturnal hypertension, and sleep disturbance." (PMID 28575038, 2017). "Taken together, these data suggest that higher central or circulating BDNF may account for hypertension and that the A variant may be linked to reduced BDNF levels." (PMID 37007871, 2023). "Therefore, elevation of the BDNF level has been proposed as “the mechanism by which physical exercise reduces blood pressure and lowers hypertension risk” in humans." (PMID 31341469, 2019). "Thus, we postulated that hypertension is associated with downregulation of BDNF‐TrkB signaling in the hippocampus, which can be rescued by exercise training through the upregulation of FNDC5 expression in skeletal muscle and brain." (PMID 31883222, 2019). "As it was a cross-sectional study, it is unclear if these associations observed are casual or elevated plasma BDNF represents a compensatory response of the disrupted lipid metabolism and hypertension, but the elevation of serum BDNF in hypertension was confirmed by our study as well." (PMID 30767081, 2019). "We hypothesized that as hypertension is a risk factor for cardiovascular diseases and BDNF is protective in cardiovascular pathology, seBDNF can be altered in hypertension." (PMID 27478486, 2016). "Decreased expression of BDNF in the endothelium was associated with hypertension." (PMID 26431274, 2015). "Plasma BDNF was the sole significant factor associated with the reverse-dippers in our multiple logistic regression analysis that included age, gender, classical cardiovascular risk factors, medical hypertension treatments, and AHI as covariates." (PMID 25153796, 2014). "BDNF is further reduced by vascular risk factors such as hypertension and poor glucose metabolism." (PMID 21876809, 2011). "However, it is not clear whether these associations are causal or the disrupted metabolism of lipids and hypertension provoke compensatory changes in serum BDNF levels." (PMID 33343231, 2020). "Thus, targeting the skeletal muscle FNDC5/BDNF pathway through endurance exercise may benefit the heart, skeletal muscle, and brain and lead to novel therapeutic approaches against hypertension and its associated comorbidities." (PMID 31883222, 2019).
Hypertension (continued). "Given that central BDNF knockdown leads to resistance to Ang II-induced hypertension, while central ERα knockdown results in heightened sensitivity to Ang II-induced hypertension, BDNF and estrogen function as physiological antagonists." (PMID 39655343, 2024). "Reduced signaling from both BDNF and estrogen can impair an individuals' ability to regulate blood pressure in response to environmental changes, potentially leading to hypertension, especially in postmenopausal women." (PMID 39655343, 2024). "In addition, Tucsek and colleagues reported that hypertension was associated with a reduced synaptic density in the mouse hippocampus and with the down-regulation of several genes that are neuroprotective, such as BDNF and Igf1, or regulate postsynaptic signal transduction events, such as Homer1." (PMID 39457698, 2024). "This priming, achieved with low dose of salt, Ang II or aldosterone, sensitizes animals to Ang II-induced hypertension by increasing BDNF levels in the PVN." (PMID 39655343, 2024). "For example, exogenous BDNF induces vasodilation in aortic rings, while hypertension suppresses BDNF expression in aortic endothelial cells." (PMID 39655343, 2024). "BDNF is related to cardiomyocyte contractility and its alterations with atherosclerosis and hypertension, and NGF plays a role in atrial autonomic OSAS-induced atrial fibrillation." (PMID 36982552, 2023). "In our study, tobacco use, and hypertension were related to significantly higher plasma BDNF levels." (PMID 39081995, 2023). "In this regard, in the context of hypertension, EX-induced enhanced BDNF expression was reported to be dependent on peripheral but not central FNDC5." (PMID 37868812, 2023). "Conversely, pathologies associated with endothelial dysfunction, such as diabetes, cerebral ischemia, high blood pressure or rheumatoid arthritis decrease cerebral BDNF expression." (PMID 37868812, 2023). "Aldosterone levels are increased in patients with hypertension, and it has been shown that aldosterone treatment significantly decreases DNA methylation and BDNF expression in the hippocampus." (PMID 36352848, 2022). "The mechanism also involves DNA methylation changes in the genes of hypertension patients, such as brain-derived neurotrophic factor, apolipoprotein E4, and estrogen receptor alpha, which contribute to learning, memory, and attention deficits." (PMID 36352848, 2022). "Serum BDNF levels are known to be modulated by various factors, including age and sex, and the presence of hypertension." (PMID 34440543, 2021). "In normal people who only have hypertension, it alters brain-derived neurotrophic factor (BDNF)-tropomyosin receptor kinase B (TrkB) signaling in the hippocampus through structural and functional changes." (PMID 31234585, 2019). "In this study, we found an irregular histopathological structural arrangement in the SHR rat cortex due to the impairment in BDNF-TrkB signaling in the cortex by the effect of hypertension." (PMID 31234585, 2019). "BDNF mRNA was increased in the quadriceps and BDNF protein was increased in the LV of SHR, while BDNF mRNA in the DG was lower in SHR, suggesting that hypertension increased BDNF expression in peripheral tissues while decreasing hippocampal BDNF." (PMID 31883222, 2019). "How can BDNF influence blood pressure, potentially playing an important role in the development of hypertension?" (PMID 30767081, 2019). "It is also suggested that the expression of BDNF in the cortex is a more effective way to approach hypertension-mediated defects." (PMID 31234585, 2019). "Our results showed that treatment with VHVV upregulates the expression of BDNF, which is an important protein related with long-term memory and neuronal cell death in hypertension rat cortex." (PMID 31234585, 2019). "But in hypertension the elevation of BDNF can also be an effect of medications as in a preliminary study after 3 months of antihypertensive therapy a tendency of BDNF increase was observed." (PMID 30767081, 2019).
Hypertension (continued). "Spontaneously hypertensive rats (SHR), a rodent model of genetic essential hypertension in humans, have markedly reduced BDNF expression in the RVLM compared to normotensive Wistar–Kyoto (WKY) rats, which is dependent on reactive oxygen species." (PMID 31883222, 2019). "Recent clinical studies have also identified a potential link between circulating BDNF levels and endothelial dysfunction, although the data were limited to metabolic syndrome and hypertension." (PMID 29409455, 2018). "In our study, the positive correlation with HDL and also with pulse pressure amplification, where higher values refer to better vascular conditions, also supports the plausible beneficial effect of BDNF in hypertension." (PMID 27478486, 2016). "As there is decrease in the brain derived neurotrophic factor (BDNF) levels in chronic diseases such as hypertension, so assessment of BNDF might establish correlation between the two." (PMID 39916293, 2025). "The favorable benefits of IF have also been demonstrated in the prevention of hypertension, where IF increased BDNF factors, activated the parasympathetic nervous system, decreased heart rate, and acted as a vasodilator on blood vessels, resulting in a drop in systolic and diastolic blood pressure." (PMID 35685418, 2022). "Second, hypertension impairs the expression of brain-derived neurotrophic factor (BDNF) and endothelial nitric oxide synthase (eNOS) in endothelial cells, which may account for the impaired dilatory capability of endothelial cells." (PMID 34881076, 2021). "Based on these findings and others, we hypothesize that the BDNF signaling pathway within the RVLM may be a viable target for the treatment of hypertension and sympathoexcitation occurring in sedentary individuals." (PMID 34721079, 2021). "The effect of hypertension on skeletal muscle BDNF expression has been largely unexplored." (PMID 31883222, 2019). "All together, these findings suggest that changes in FNDC5/BDNF signaling may play a role in cardiovascular pathologies such as hypertension or MI." (PMID 31883222, 2019). "In summary, BDNF is required for normal carotid body innervation, baroreceptor function and heart rate regulation and these effects can be blunted in pathological conditions, such as high salt intake, which can lead to the development of hypertension." (PMID 30767081, 2019). "Our results show that hypertension reduced the amount of BDNF, which is an important protein related with long-term memory in the cortex, and suggests that the hypertension impaired long-term memory, downregulated BDNF, and altered dendritic signals and neurogenesis in the cortex." (PMID 31234585, 2019). "Our results suggest a complex psychosomatic involvement of BDNF in the pathophysiology of hypertension, where hyperthymic affective temperament may have a protective role." (PMID 27478486, 2016). "In conclusions, our results suggest a complex psychosomatic involvement of BDNF in the pathophysiology of hypertension, where hyperthymic affective temperament may have a protective role." (PMID 27478486, 2016). "Meanwhile, a recent study reported that, in a rat model of hypertension produced by salt loading, brain-derived neurotrophic factor (BDNF)-tropomyosin-receptor-kinase B (TrkB) activation causes the down-regulation of KCC2 and the depolarizing shift of EGABA in MNCs." (PMID 26017151, 2015). "In addition, VMH BDNF was negatively involved in stress-induced hypertension." (PMID 41219904, 2025). "Recently, growing evidence highlightsthat the BDNF/TrkB pathway is expressed in the cardiovascular system andclosely associated with the development and outcome of cardiovascular diseases (CVD), including coronary artery disease, heart failure, cardiomyopathy, hypertension, and metabolic diseases." (PMID 33477900, 2021). "Furthermore, hypertension was associated with significantly reduced BDNF mRNA in the DG of the hippocampus but not the CA regions, PVN, or RVLM." (PMID 31883222, 2019).
Hypertension (continued). "Thus, BDNF appears to have roles in energy metabolism, autonomic function, nocturnal hypertension, and sleep disturbance, and may also be protective against cardiovascular diseases and death through both neural and non-neural pathways via TrkB signaling." (PMID 28575038, 2017). "However, to the best of our knowledge, no other study has explored the association between BDNF and renal outcome together with autonomic function, sleep quality, and nocturnal hypertension." (PMID 28575038, 2017). "As stored BDNF is released from platelets during clotting and in essential hypertension, increased platelet activation is a trigger of hypercoagulable state, our finding that platelet count is positively correlated with seBDNF may refer to a chief source of seBDNF in this pathological condition." (PMID 27478486, 2016). "Regardless of these potential limitations, our findings are the first to show a mutual relationship among BDNF, the autonomic nervous system, and reverse-dippers of nocturnal hypertension, and provide an important first step to answer pressing pathophysiological questions in regard to hypertension." (PMID 25153796, 2014). "The findings of the effect of DMM on BDNF and how it affects the health, quality of life, and emotional state of individuals might be used to give early intervention to patients with history of parents having hypertension, working in stressful conditions and emotional imbalance state." (PMID 39916293, 2025). "This suggests that BDNF serves as a critical hub for multiple pathways, enhancing RAS sensitivity and exacerbating the development of hypertension." (PMID 39655343, 2024). "Brain-derived neurotrophic factor (BDNF) has recently been recognized as a cardiovascular regulator particularly in the diseased condition, including coronary artery disease, heart failure, cardiomyopathy, and hypertension." (PMID 34202148, 2021). "In additional multivariable logistic regression models, BDNF, BDNF/Adip ratio, hypertension and respiratory diseases were shown to be predictors of ICU admission, while hypertension and respiratory diseases were independent predictors of patients' risk of death." (PMID 34957187, 2021). "In addition, our results suggest that resveratrol not only attenuated increases in superoxide levels in the NTS and increased BDNF expression, but also increased the antioxidant capacity of the NTS in rats with hypertension." (PMID 30301188, 2018). "Hypertension has widely studied psychosomatic connections; however, the role of BDNF in this condition has not been extensively evaluated yet." (PMID 27478486, 2016). "Hypertension impairs hippocampal neurogenesis in adult mice, affecting CA1 neurons, dendritic arborization, and long-term memory, which may be related to the down-regulation of the BDNF signaling pathway." (PMID 36352848, 2022). "Interestingly, in contrast, decreased endothelial BDNF expression was found in hypertension, so the source of higher BDNF serum and plasma levels in hypertension is probably not the endothelial cells." (PMID 30767081, 2019). "However, after adjusting for BDNF, BDNF/Adip ratio, Age, and BMI, logistic regression showed that hypertension and respiratory diseases are not predictors of death, being Age the only independent variable holding significant association with Death in either multivariable models considered." (PMID 34957187, 2021). "These events raise the possibly that the development of sympathoexcitation in CHF or some forms of hypertension could be due to the interplay between Ang II-elicited increases in neuronal activity in brainstem nuclei, such as the RVLM, and aberrant development of long-term potentiation through BDNF." (PMID 26537343, 2015).
Parkinson’s (67 papers, 2012 to 2026). "In PD, a reduction in BDNF expression in SN might contribute to the death of DA neurons because inhibiting BDNF expression in the SN causes parkinsonism in the rat." (PMID 36555817, 2022). "Furthermore, exercise training has also been found to increase BDNF levels and improve motor symptoms in patients with Parkinson’s, though controversies exist regarding the best exercise intensity and pathways for elevated circulating BDNF levels in this case." (PMID 40430064, 2025).